RN7SL608P (RNA, 7SL, cytoplasmic 608, pseudogene)
Gene: Miscellaneous RNA gene on chromosome 17 (2,680,958 to 2,681,236, forward strand). Ensembl gene ENSG00000239884.
Homologues: Orthologues: macaque Metazoa_SRP (94% identical). Paralogues in human: RN7SL1 (88% identical), RN7SL3 (88% identical), RN7SL2 (87% identical), RN7SL45P (85% identical), RN7SL709P (85% identical), RN7SL566P (85% identical), RN7SL126P (84% identical), RN7SL220P (84% identical), RN7SL88P (84% identical), RN7SL493P (84% identical), RN7SL166P (84% identical), RN7SL321P (84% identical), and 711 more.